TNF (tumor necrosis factor)
Diseases named in the same sentence as TNF in open-access papers (continued):
Sharing a sentence is not in itself a finding about the gene and the disease.
colitis (continued). "In the present study, we further demonstrate that local TNF-α and IL-1β expressions are decreased after HQT or mesalazine treatment in rats with TNBS-induced colitis." (PMID 26347453, 2015). "We conclude that HFD delays the healing of colitis in trained rats via decrease in CBF and plasma IL-1β, TNF-α, TWEAK, and leptin levels and the release of protective irisin." (PMID 25684862, 2015). "Mesalamine establishes angiogenic balance by reducing angiostatin and endostatin and induced TNF-α and MMP-9 activity in experimental colitis." (PMID 26839731, 2015). "Experimental colitis was quantified in the rat model, macroscopically and by measuring the activity of tissue MPO and iNOS and levels of TNFα and IL-1β." (PMID 25949237, 2015). "Treatment with HBO normalized IL-1β, TNF-α, CINC-1 and IL-10 (P < 0.05) in rats subjected to colitis by TNBS." (PMID 25926972, 2015). "Administration of L. plantarum and L. brevis reduced IL1β, TNFα, and IFNγ, as well as the protein expressions of IL1β and IL6, and the signs of colitis in DSS-induced colitic mice." (PMID 26347738, 2015). "In HFD animals, the exercise significantly accelerated the healing of colitis, raised the plasma levels of IL-6 and irisin, downregulated the expression of IL-1β, TNF-α, and Hif1α, and significantly decreased the plasma IL-1β, TNF α, TWEAK, and leptin levels." (PMID 25684862, 2015). "Baill.var.hainanensis Tsiang showed a potent anti-inflammatory effect on an experimental murine colitis model induced by DSS, decreasing the level of proinflammatory molecules such as activated NF-κB, TNF-α and IL-17." (PMID 26437418, 2015). "There was a significant increase in the levels of IL-1β, IL-6, IL-17, TNF-α and INF-γ in the plasma of the mice with colitis." (PMID 25625560, 2015). "In colitis group induced by TNBS, the data revealed significant increase (P<0.01) in the colonic expression of TNF-α(6.17-fold), iNOS (21.38-fold) and COX-2 (11.58-fold)." (PMID 26469068, 2015). "HLA-B27 associated disease progression in rats was accompanied by the expansion of pro-inflammatory CD4+ T-cells expressing IL-17, TNF and IFN-γ as early as 6 weeks of age, and clinical symptoms (colitis) appeared at approximate 10 weeks of age." (PMID 26125554, 2015). "It has been demonstrated that a deficiency in CD69 leads to increased production of pro-inflammatory cytokines (such as TNF-α, IFN-γ, and IL-21), reduced FoxP3+ regulatory T-cell function, impaired oral tolerance, and more severe colitis." (PMID 26206376, 2015). "Finally, in rats with chemically-induced colitis, treatment with G ameliorated symptoms of colitis, while decreasing both systemic and colonic inflammation, as measured by serum concentrations of IL-8 and amyloid P component, and colonic expression of NF-kB, IL-1β, and TNFα, respectively." (PMID 25719429, 2015). "2′,4′,6′-Tris (methoxymethoxy) chalcone (TMMC) protected against TNBS induced colitis and was able to inhibit MMP-7 upregulation induced by TNF-α in HT-29 cells." (PMID 25948887, 2015). "The administration of CBS effectively reduced the mRNA expression of TNF-α, IL-1β, and IL-6 in the colon tissue of mice with DSS-induced colitis." (PMID 26579201, 2015). "The development of experimental colitis in HFD rats was accompanied by the fall in CBF, the increased expression of proinflammatory cytokines IL-1β, TNF-α, and TWEAK, and decreased release of protective adipokines (e.g., adiponectin)." (PMID 25684862, 2015). "In our study, the expression of the Th1-type cytokines IFN-γ, TNF-α and IL-1β in the colon is down-regulated in response to MMF after TNBS-induced colitis in our IBD mouse model, after both three and 10 days." (PMID 26561804, 2015). "Colon Cav-1 levels were significantly decreased in TNBS-induced colitis mice when compared to normal mice and also inversely correlated with colon inflammation scores and proinflammatory cytokine levels (IL-17, IFN-γ and TNF) significantly." (PMID 25756273, 2015).
colitis (continued). "Pro-inflammatory cytokines such as TNFα, IL1β, and IL6 play pivotal roles in the pathogenesis of colitis." (PMID 25072851, 2014). "Administration of TLM lowered TNF-α, PGE2 and IL-10 by 49%, 39% and 51% respectively, as compared to TNBS colitis group." (PMID 24831514, 2014). "Our current study showed that direct stimulation of a cell line of colonic epithelial cells with IL-25 increased expression of IL-6, TNFα, as well as IL-8 and CCL2, providing a potential mechanism by which IL-25 contributes to DSS-induced colitis." (PMID 25937893, 2014). "We have found the serum TNF-α, IFN-γ, and neopterin values to be significantly increased in our rat colitis model." (PMID 25032214, 2014). "The mRNA transcripts of the cytokines/chemokines TNFα, BLC, M-CSF and IL-1 receptor antagonist are detected in distal colon homogenates of water-receiving intact and DSS-treated colitis mice." (PMID 25265225, 2014). "The NF-κB regulates the expression of several proinflammatory genes including TNF-α, COX-2 and iNOS that play key roles in IBD and TNBS colitis." (PMID 24831514, 2014). "Our data also described an upregulation of the inflammatory status with increased levels of TNF-α and PGE2 along with NF-κB, COX-2 and iNOS in rats with TNBS colitis." (PMID 24831514, 2014). "It has been demonstrated that TNFα, as well as other cytokines (IL-1β and IL-6) are elevated in colon tissue in response to DSS-induced colitis by our group and countless others." (PMID 25460165, 2014). "Here, after demonstrating the beneficial effect of central cholinergic activation by a M1mAChR agonist in DNBS-colitis, we demonstrate that this effect is accompanied by a downregulation of IFN-γ and IL-17, IL-1 β, IL-6 and TNF-α levels in colonic tissues." (PMID 25295619, 2014). "The levels of TNF-α and IFN-γ increased, but IL-6, IL-17A and IL-4 decreased in lamina propria (LP) of colon in immune milk-fed mice with DSS-induced colitis." (PMID 24686517, 2014). "This notion is supported by the reports that human umbilical cord blood MSCs reduced colitis in mice, and that human ERCs were able to suppress cell proliferation, IFN-γ and TNF-α production in a mouse mixed lymphocyte reaction." (PMID 25475342, 2014). "A bioflavonoid derived from the seeds of Garcinia kola, kolaviron, exhibits an anticolitis effect by reducing nitric oxide, myeloperoxidase activity, TNF-α, and IL-1β in DSS-induced colitis mice." (PMID 25045208, 2014). "Cytokines including IL-6 and TNF-α, which play a crucial role in acute DSS-induced colitis model, were analyzed." (PMID 24948848, 2014). "Increased expression of cytokines, such as IL-1β, IL-6, TNF-α, and interferon-γ (IFN-γ), is observed after TNBS treatment, suggesting that cytokines are involved in the pathogenesis of TNBS-induced colitis." (PMID 24995035, 2014). "As expected, we observed that MMP13−/− mice were less sensitive to DSS-induced colitis than MMP13+/+ mice and that this was correlated with reduced bioactive TNF levels." (PMID 23723167, 2013). "Both dosages of sinomenine significantly decreased the mRNA and protein expression levels of c-Maf, TNF-α and IFN-γ, which elevated in TNBS-induced colitis." (PMID 24066068, 2013). "Specifically, treatment of mice with IL-4 or IL-10 resulted in a marked improvement in the histological appearance of the distal colon and suppression of Th1-cell type cytokines, such as IFN-γ, TNF-α and IL-6 in TNBS-induced murine colitis." (PMID 24314293, 2013). "Both TNF and MUC2 play a major role in the development of DSS-induced colitis via their involvement in epithelial barrier function, and they are altered before epithelial cell damage occurs." (PMID 23723167, 2013). "In the present study, we further evaluated the influence of sinomenine on miR-155, c-Maf, TNF-α and IFN-γ expression levels and investigated the possible mechanisms of sinomenine involving miR-155 in TNBS-induced colitis in mice." (PMID 24066068, 2013).
colitis (continued). "Given the critical importance of TNF-α and EGF on intestinal inflammation, mucosal repair, and the development of cancer, the identification of signaling interactions between them may provide invaluable insight in the pathophysiology of colitis-associated cancer." (PMID 23688423, 2013). "Here, we demonstrate, for the first time, that enhanced EGFR expression induced by TNF-α facilitates GPCR-mediated EGFR transactivation in colonic myofibroblasts, providing an important mechanism for stromal COX-2 over-expression that may predispose to the development of colitis-associated cancer." (PMID 23688423, 2013). "Prunus mume mixture treatment decreased the expression of TNF-α, COX-2, IL-4, STAT6, INF-γ, STAT1 in mice with DSS-induced colitis." (PMID 23783459, 2013). "In conclusion, this study has shown that sinomenine suppresses major pro-inflammatory cytokines TNF-α and IFN-γ, and attenuates TNBS-induced colitis probably through down-regulation of miR-155 and c-Maf." (PMID 24066068, 2013). "Pro-inflammatory cytokines such as TNF-α, IL-1β, and IL-6 were detectable in both SIGNR3−/− and wild-type mice upon induction of DSS colitis." (PMID 23882266, 2013). "To confirm the histological results, we checked mRNA expression patterns of TNF-α, iNOS and IL-10 in colon tissue obtained from DSS induced colitis mice following administration of CO and LiCl." (PMID 24349609, 2013). "The levels of TNF-α and CINC-3 were significantly raised in the colon following induction of colitis by DSS." (PMID 22562255, 2012). "In the present study, we observed an elevation of the proinflammatory cytokines, such as TNF-α and IL-1β, in DSS colitis tissue." (PMID 23125487, 2012). "Proinflammatory cytokines (e.g., TNF-α, IL-1β, and IL-6) liberated from macrophages, neutrophils, and endothelial cells were shown to be overproduced in TNBS-induced colitis and in human IBD." (PMID 22888336, 2012). "In fact, proinflammatory cytokines of the Th1-type of immune response such as TNF-α and IL-1β are known to be present in high levels in CD and in TNBS-colitis." (PMID 22432015, 2012). "The increase in the amount of IL-1β and TNF-α mRNA and protein in the mice with DSS-induced colitis was reduced significantly following the treatment with picroliv." (PMID 23125487, 2012). "In both experimental colitis models, TNF-α and IL-6 levels were elevated but treatment with iMSCs was accompanied by a strong reduction in the amount of TNF-α and IL-6 in the colon." (PMID 23049573, 2012). "For example, tumor necrosis factor-alpha (TNF-α), which is released by immune cells, has been shown to promote cancer in experimental colitis." (PMID 24710489, 2012). "A significant increase of mRNA and protein expression of IL-1β and TNF-α, as assessed by real-time quantitative RT-PCR and ELISA, respectively, was observed in saline-treated mice with DSS-induced colitis compared with the normal control group (P < 0.05)." (PMID 23125487, 2012). "Pro-inflammatory cytokines like macrophage migration inhibitory factor (MIF), IL-1β and TNF-α predominate in inflammatory bowel diseases (IBD) and TNBS colitis." (PMID 23166707, 2012). "TNF-α, IFN-γ, MCP-1, IL-17, KC and Eotaxin-1 have been shown to be over-produced during inflammatory diseases, including IBD or in experimental model of colitis." (PMID 21858153, 2011). "All doses of anthocyanins extract from blueberries significantly reversed the increase in IL-12, TNF-α and IFN-γ levels, which were all high in TNBS control, and the production of IL-10 was up-regulated, which was inhibited in TNBS-induced colitis in mice." (PMID 21785630, 2011).
colitis (continued). "Along with the higher number of immune cells in the colitis + HFD group, we found overexpression of TNFα, IL-6 and MCP1/CCL2 compared to the other three groups." (PMID 22073943, 2011). "Rb1 and compound K appear to block IRAK-1 and NFκB activation and thereby reduce pro-inflammatory cytokines, IL-1β, TNF-α and IL-6 and cytokine effectors iNOS and Cox-2 in 2,4,6-trinitrobenzene sulfonic acid (TNBS)-treated mice, another model of colitis." (PMID 22070864, 2011). "Treatment with TNF-α neutralizing antibody significantly decreased DAI, delayed the acute phase of colitis and effectively curtailed alterations in the expression and production of TNF-α and mucins." (PMID 21949848, 2011). "Since TNF-α have been shown to be a critical component of the course of GvHD in general and for the increased paracellular permeability in DSS induced colitis, we next analysed expression of this proinflammatory cytokine in specimen of the jejunum by PCR." (PMID 21977944, 2011). "First, we analyzed production of pro-inflammatory cytokines in the colonic homogenates of the chronic DSS-induced colitis mice, and found that ILK-ko mice had significant reductions (up to 50%) in their levels of TNF-α, IFN-γ and IL-12p40." (PMID 21806815, 2011). "In our study, the increase in adipose tissue inflammation seen in the Colitis + HFD group was confirmed by the increase in CLS, activated macrophages, lymphocytes and neutrophils and the overexpression of adhesion molecules, TNFα, IL-6, MCP1/CCL2 and TLR4." (PMID 22073943, 2011). "We analyzed the effect of punicic acid on TNFα-induced neutrophil upregulation of ROS production in vitro and on TNBS-induced rat colon inflammation." (PMID 19649246, 2009). "In order to study the TNF-independent role of TAK1 in the intestinal barrier, we utilized adult TNFR1KO/ TAK1IEKO mice and examined sensitivity to chemical-induced acute colitis." (PMID 19234607, 2009). "We demonstrate that local and/or systemic expression of the TNF-α, IFN-γ, and CXCR3 ligands are increased during live Mycobacteria-enhanced colitis." (PMID 18533024, 2008). "The availability of LMP-420, a small-molecule, orally-active inhibitor of TNF production, provided us an attractive opportunity to define the potential role of TNF in the murine model of DSS-induced colitis, a commonly-used model of inflammatory bowel disease." (PMID 18331642, 2008). "The current study suggests NK and NKT cells collaborate to produce CXCL10, IL-12p40, TNF-α, and IFN-γ to recruit and stimulate CXCR3+ leukocytes in either inductive or effector sites during colitis." (PMID 18533024, 2008). "Relative amounts ofIL-1β, IL-6, GM-CSF, and TNFα mRNAs (for full gene names) weresignificantly higher in animals with TNBS-induced colitis (group D) than in thecontrol sham-treated animals." (PMID 18288268, 2007). "In fact, the murine models of TNFα-related diseases, TNBS-induced colitis and collagen antibody-induced arthritis, were exacerbated in BM-hIL-32 mice." (PMID 17078892, 2006). "Samples were collected 7 days after colitis induction, for intestinal bacterial flora, bacterial translocation, short chain fatty acids (SCFAs), myeloperoxidase (MPO), cytokines (IL-1β, TNF-α, IL-10 and TGF-β) and malondialdehyde (MDA)." (PMID 17069659, 2006). "Similarly, the concentrations of inflammatory factors in the blood of colitis mice in the A. actinomycetemcomitans gavage group were also significantly higher than those in the DSS group (IL-6, P = 0.002; IL-1β, P = 0.002; TNF-α, P = 0.004)." (PMID 41531455, 2026). "In addition, the results implied that the mice in TNBS + MSC + SIS group had alleviated colitis compared with the TNBS + MSCs group, and the interleukin (IL)-1β and tumor necrosis factor-α (TNF-α) levels in the serum also decreased." (PMID 42218603, 2026).
colitis (continued). "In this study, the levels of IL-1β, IL-6, and TNF-α in enteritis model mice were significantly higher than those in the control group, indicating that systemic inflammation was triggered when DSS-induced colitis." (PMID 40238292, 2025). "Such animals produce reduced amounts of IL-1β and TNF and are protected from acute, but not chronic, experimental colitis." (PMID 41194916, 2025). "TNF-α and MCP-1 were significantly upregulated in the vehicle-treated colitis group compared to healthy controls (0.6 ± 0.1 vs. 2.9 ± 0.4 and 2.5 ± 0.3 vs. 32.6 ± 5.0, respectively; p < 0.0001), highlighting the activation of macrophages and monocyte recruitment in the inflamed colon." (PMID 40869234, 2025). "Moreover, we identified that TNF‐α destabilized ACSS2 mRNA by enhancing its m6A modification level, thereby aggravating colitis." (PMID 40650658, 2025). "Furthermore, by using TNF-α to establish an inflammatory model in Caco-2 cells, it has been further confirmed that SPDD can indeed alleviate colitis in mice by downregulating the expression of MAPK4." (PMID 40238233, 2025). "In our work, the levels of TNF-α and IL-6 did not statistically significantly increase in Mcpt-4fl/fl colitis mice compared with that in control Mcpt-4fl/fl mice, but there was a minor increase." (PMID 40697820, 2025). "Additionally, Rhy lowered serum levels of inflammatory cytokines IL-6, TNF-α, CXCL1, and IL-1β in colitis mice." (PMID 41031160, 2025). "The DSS group showed a significant increase in the gene expression levels of TNF-α, IL-1β, and IL-6 in the colon (p < 0.001), which was consistent with the serum findings, indicating a strong correlation between DSS-induced colitis and heightened cytokine expression in the colon." (PMID 40238198, 2025). "In a mouse model of colitis induced by dextran sulfate sodium, BUD was found to inhibit the expression of cytokines (e.g., myeloperoxidase/MPO and tumor necrosis factor/TNF-α) and inflammatory enzymes (e.g., cyclooxygenase-2/COX-2 and inducible nitric oxide synthase/iNOS)." (PMID 40284499, 2025). "These infiltrates are typically accompanied by increased levels of proinflammatory cytokines, including IL-6/17, interferon-gamma (IFN-γ), and tumor necrosis factor alpha (TNF-α), which are thought to mediate mucosal injury and contribute to the severity of colitis." (PMID 40726872, 2025). "Additional in vivo models of colitis induced by dextran sodium sulfate or TNBS have demonstrated that aronia extracts reduce pro-inflammatory cytokines (e.g., TNF-α, IL-1β), oxidative stress markers (MDA) and restore endogenous antioxidant enzymes such as catalase and GPx." (PMID 41515306, 2025). "Oxidized berberine reduces TNF-α levels by 55% in colonic tissues of 2,4,6-Trinitrobenzenesulfonic acid (TNBS)-induced colitis rats through inhibition of the macrophage NF-κB pathway, while simultaneously reducing neutrophil infiltration (40% decrease in MPO activity)." (PMID 41480384, 2025). "It was found that RES may prevent barrier defects and inflammation by inhibiting neutrophil infiltration in mice with colitis, and RES has also been proven to inhibit TNF-α-induced inflammatory signaling and IL-8 production in Caco-2 human intestinal cells." (PMID 40761281, 2025). "On the other hand, increases in the population of Lactobacillus in experimental colitis were paralleled by a distinct negative correlation with colonic TNF-α levels." (PMID 40056427, 2025). "The marked changes in TNF and IL-10-specific signaling due to DSS-colitis provide evidence that inflammation in the body may lead to a reduction in the signal-to-noise at the individual neuron level." (PMID 40268933, 2025). "Isobutyric acid pretreatment significantly downregulated pro-inflammatory gene expression (IL-1β, TNF-α, NLRP3, and ASC) while upregulating tight junction components (occludin, claudin-1, and zo-1), demonstrating its protective role against DSS-induced colitis." (PMID 41171006, 2025).